IL6 (interleukin 6)
Diseases named in the same sentence as IL6 in open-access papers (continued):
Sharing a sentence is not in itself a finding about the gene and the disease.
tumor (continued). "On the other hand, CA IX and GLUT-1 immunohistochemistry was performed on one tumor biopsy taken at the periphery of the tumor field, and VEGF and IL-6 values were measured as systemic serum levels." (PMID 15847702, 2005). "Other tumor characteristics such as tumor stage and differentiation grade were not correlated with either perfusion-CT, serum VEGF or serum IL-6 levels." (PMID 15847702, 2005). "In this report, we investigated the ability of peripheral (PBL) and tumor- infiltrating (TIL) lymphocytes of undifferentiated NPC patients to produce in vitro three interleukins (IL-2, IL-6, IL-10) and three immunoglobulin isotypes (IgM, IgG, IgA)." (PMID 15450122, 2004). "The expression of cytokines such as IL-2, IL-6 and IL-10 in NPC has been studied mainly on tumor biopsies using immunohistochemical and molecular techniques." (PMID 15450122, 2004). "Interleukin-6 (IL-6) and tumour necrosis factor-alpha (TNF-α) are important multifunctional cytokines involved in tumour growth and metastasis." (PMID 15150588, 2004). "In vitro, it has been demonstrated that factors that can be produced by tumour cells, including vascular endothelial growth factor (VEGF), M-CSF and IL-6, inhibit DC maturation from CD34+ cells." (PMID 14562018, 2003). "In contrast, the IL-6+LNT group showed a marked reduction in both tumor volume and weight, indicating that LNT could effectively inhibit the tumorigenic effect of IL-6, thereby suppressing tumorigenesis." (PMID 41602823, 2026). "Modulation of tumor-supportive signaling was examined by measuring VEGF and IL-6 secretion." (PMID 42075801, 2026). "IL-6 can also activate the JAK/STAT3 signaling pathway, which in turn promotes the expression of genes that are involved in immune evasion, metastasis, and tumor cell survival." (PMID 41497141, 2026). "Soluble mediators such as cytokines (IL-6, TNF-α), chemokines (CXCL12, CCL2), and immune checkpoints (PD-L1/PD-1, CTLA-4) further exacerbate the immunosuppressive state of HCC TME, forming a vicious cycle that facilitates tumor immune escape and progression." (PMID 41602547, 2026). "Finally, we found that combining IL-6 and EGFR blockade effectively controlled pain and tumor growth simultaneously in SWN models." (PMID 41758723, 2026). "However, paracrine signalling mediates their role in HCC cell proliferation, migration, invasion, as well as enhancing tumour growth, as they activate pathways, including NF-κB, ERK, IL-6/STAT3 and Wnt/β-catenin." (PMID 41476776, 2026). "Pathophysiologically, CAR T‐cell recognition of tumor cells induces a burst of IFN‐γ and other effector cytokines that activate monocytes/macrophages, which then amplify the inflammatory cascade through secretion of IL‐6, IL‐1, IL‐10, and TNF." (PMID 41207679, 2026). "In addition, CAFs secrete immunomodulatory cytokines, including TGF‐β and IL‐6, and proangiogenic factors such as VEGF and bFGF, thereby fostering a tumour‐supportive microenvironment." (PMID 41486497, 2026). "Moreover, ABCB5-positive cells contribute to the formation of an immunosuppressive microenvironment by secreting cytokines (IL-6, IL-8, TGF-β) and expressing immune checkpoint ligands, such as PD-L1, thereby favoring tumor progression and a poor prognosis." (PMID 41681896, 2026). "Immune processes included IL6/JAK/STAT3 signaling, Type I and II Interferon Responses, Toll-like Receptor signaling, and T cell receptor signaling, highlighting a more immunoreactive tumor microenvironment." (PMID 41493679, 2026). "Importantly, P. aeruginosa–induced pyroptosis was accompanied by a marked increase in inflammatory cytokines, including IL-6 and TNF-α, and a significant upregulation of PD-L1 expression on tumor cells." (PMID 41484455, 2026).
tumor (continued). "Rather than a passive byproduct of disease, ovarian cancer ascites comprises a bioactive reservoir rich in cytokines (e.g., TGF-β, IL-6, IL-8), growth factors, lipids, ECM components, and extracellular vesicles, as well as diverse tumor, immune, and stromal cell populations." (PMID 41590379, 2026). "The anti-tumor effect of IL-37 results from the suppression of tumor-promoting cytokines, such as IL-1β, which activates IL-6 and TNF, direct effects on tumor cells, and reduction of cell proliferation by interfering with NF-κB, MAPK, and signal transducer and activator of transcription 3 (STAT3)." (PMID 41596472, 2026). "The immune processes included IL6/JAK/STAT3 signaling, Type I and II Interferon Responses, Toll-like Receptor signaling, and T cell receptor signaling, highlighting a more immunoreactive tumor microenvironment." (PMID 41493679, 2026). "The IL-6/JAK2/STAT3 pathway upregulates DNA methyltransferase 1, promoting tumor progression." (PMID 40530335, 2025). "These microbial-metabolic perturbations synergistically activate NF-κB and STAT3 signaling pathways, generating a pro-inflammatory cytokine milieu (IL-6, TNF-α, IL-1β) that establishes a tumor-promoting microenvironment through autocrine and paracrine cascades." (PMID 40919140, 2025). "Hence, MSCs were pretreated for 48 h with TGF-β1, IL-6 or IFN-g and subsequently used as a feeder for tumor cell growth." (PMID 40842027, 2025). "CAFs also couple tumor-cell plasticity to immune suppression through mediators such as IL-6/JAK–STAT3, TGF-β, and CXCL12; after blockade of a single node, alternative routes are often activated, leading to compensatory escape." (PMID 41514658, 2025). "CAFs promote tumour progression by secreting ECM components, enzymes, cytokines, chemokines, and growth factors while modulating T-cell responses and angiogenesis via TGF-β, IL-6, CXCL9, and VEGF." (PMID 40361472, 2025). "Additionally, IL-6 directly suppresses the secretion of IFN-γ from CD8+ T cells, thereby reducing their anti-tumor efficacy." (PMID 41368628, 2025). "Our data suggest that CD8+ T cells in NSCLC patients were in a state of exhaustion and combined blockade of IL-6 and PD1 to restore CD8+ T cell function to inhibit tumor growth may be an effective clinical strategy for the treatment of NSCLC." (PMID 40040705, 2025). "TAMs release TGF-β, IL-1β, and IL-6, which increase MMP-9 in tumour cells." (PMID 40361472, 2025). "Results demonstrated a 4.6-fold increase in IL-6 and a 7.4-fold increase in IL-23 mRNA expression in tumor tissues compared to adjacent non-tumorous tissues (P < 0.001 and P < 0.0001, respectively)." (PMID 40612845, 2025). "Beyond secreting soluble factors, CAFs actively remodel the tumor immune microenvironment through exosome-mediated delivery of PD-L1, TGF-β, IL-6, CXCL12, and matrix metalloproteinases, directly impairing CD8+ T-cell function and promoting Treg cell and MDSC recruitment." (PMID 41439998, 2025). "A common immunopathogenic mechanism across many of these cancers is the activation of the MyD88/NF‐κB axis, which drives the secretion of pro‐inflammatory cytokines (e.g., IL‐6, TNF‐α), promotes angiogenesis, and upregulates anti‐apoptotic genes, thereby creating a tumor‐supportive microenvironment." (PMID 40922674, 2025). "This suggests that the inhibition of IL-6 and TNF-α could lead to reducing tumour growth and improving patient outcomes." (PMID 40544399, 2025). "Therefore, therapeutic interventions aimed at inhibiting IL-6 and TNF-α signalling pathways can potentially reduce inflammation and tumour proliferation." (PMID 40544399, 2025). "Moreover, TAS-115 significantly attenuated tumor-promoting cytokines, including TNF-α, IL-6, and VEGF-α, suggesting a potential role in modulating the inflammatory TME." (PMID 41289612, 2025).
tumor (continued). "Notably, this balance shifts throughout tumor progression: early-stage NSCLC, characterized by low TGF-β and high IL-6, favors Th17 polarization, whereas advanced stages, enriched in TGF-β, promote Foxp3 expression and Treg dominance." (PMID 41181112, 2025). "In return, TAMs support and expand CSC properties through multiple mechanisms, including the secretion of IL‐6, TGF‐β, MFG‐E8 and extracellular vesicles, direct cell–cell interactions, and remodeling of ECM, ultimately reinforcing cancer stemness and tumor malignancy." (PMID 41346572, 2025). "The IL-6/sIL-6R complex subsequently triggers phosphorylation and activates two key signaling cascades: JAK/STAT3 and PI3K/AKT leading to promote chronic inflammation, epithelial–mesenchymal transition, and tumor angiogenesis." (PMID 41256010, 2025). "Modulating cytokines like IL-6 and TNF-α could potentially shift the tumor microenvironment to support AR-targeting therapies." (PMID 40008000, 2025). "To determine the predominant myeloid populations that infiltrated the tumor in the absence of IL-6 signaling, we performed deconvolution analysis to calculate the relative enrichment of different myeloid subsets." (PMID 39653766, 2025). "Furthermore, activated CAFs release SDF-1/CXCL12, OPN, periostin, galectin, THBS2, MFGE8, and diverse cytokines such as IL-6 and IL-32, which promote the EMT, tumor invasion, and tumor metastasis." (PMID 40352270, 2025). "Spatial heterogeneity in the TME, including CD8+ T cell exclusion from tumor cores and enrichment of immunosuppressive M2 macrophages or Tregs, is compounded by CAF-mediated stromal barriers (e.g., IL-6, VEGF), which physically and biochemically restrict T cell infiltration." (PMID 40563359, 2025). "Moreover, El1405 intervention significantly increased the levels of TNF-α, INF-γ, and CD8 in the tumor microenvironment, while decreasing the levels of CD4, IL-6, IL-10, and TGF-β." (PMID 40568973, 2025). "Among the factors released by tumor cells, the most significant for SKM protein homeostasis include members of the TGF-β superfamily (such as activin A and myostatin), Hsp70 and Hsp90, TNF-α and interleukins (e.g., IL-1α and IL-6)." (PMID 41218549, 2025). "SASP secretes IL-6, IL-8, MMPs and TGF-β, remodeling the tumor microenvironment." (PMID 40510156, 2025). "MHC class I downregulation: Tumor cells may reduce the expression of MHC class I molecules via IL-2 and IL-6 produced by CAFs, thereby evading recognition and killing by TILs." (PMID 40805183, 2025). "The IL-6/signal transducer and activator of transcription 3 (STAT3) pathway promotes VM formation by upregulating key regulators such as VE-cadherin and MMP2, while also contributing to chemotherapy resistance and tumor recurrence." (PMID 41400702, 2025). "The tumor microenvironment (TME) is a significant barrier, stimulating immunosuppressive variables such as MDSCs, M2-polarized macrophages, and cytokines, including IL-6, IL-10, and TGF-β, which restrict antitumor immunity." (PMID 40075634, 2025). "Moreover, it led to a rise in the production of effector cytokines TNFα and IFNγ, while simultaneously reducing the levels of immunosuppressive cytokines IL6 and IL10 in tumor tissues." (PMID 40332725, 2025). "Comparable techniques aimed at other SASP components—such as IL-6, MCP-1, and GM-CSF are being explored to diminish tissue-level inflammation while maintaining advantageous senescence effects, including wound healing and tumor suppression." (PMID 40507795, 2025). "IL-6 decline following surgical removal of the tumor supported a non-autoimmune source of inflammation." (PMID 41552135, 2025). "Moreover, investigations revealed that in the LLC tumor model, the knockdown of ORMDL3 led to a significant increase in the expression of ISGs, including Ccl5, Cxcl10, Tnf, and Il6, compared to the control group." (PMID 40126553, 2025).
tumor (continued). "Poly(I: C) is formed by the polymerization of inosinic acid and cytidylic acid and well known as an agonist of Toll-like Receptor 3 (TLR 3) that can stimulate tumor cells to secrete immune factors, such as IL-6 and IFN-α, and then activate the tumor immune response." (PMID 39743555, 2025). "Additionally, elevated LDL levels correlate with increased levels of proinflammatory cytokines, such as IL-6 and TNF-α, which are thought to support tumor growth and metastasis." (PMID 41245411, 2025). "Analysis of tumor tissues indicated that, compared to the control group, the concentrations of TNF‐α were significantly elevated in the CB group, AKK group, and CB‐AKK combined group, whereas the concentrations of IL‐6 and IL‐10 were significantly reduced." (PMID 40497373, 2025). "Consistent results were achieved for all 94 paired tumour–normal samples for TNF-α and IFN-γ, for 93 paired samples for TGF-β1 and IL-1α, for 90 paired samples for IL-1β and IL-12, and for 87 paired samples for IL-2 and IL-6 expression." (PMID 41465261, 2025). "Besides adipokines, CAAs secrete pro-inflammatory cytokines like IL-6 and IL-8; IL-6 activates the JAK/STAT3 signaling pathway in tumor cells, promoting their growth and metastasis." (PMID 40784879, 2025). "To determine whether soluble factors from tumor cells could also induce IL6 production in immune cells, we exposed THP1 cells to MDA-MB-231 conditioned media for 24 h and measured IL6 protein levels." (PMID 41514627, 2025). "In contrast, N2 TANs possess regular or circular nuclei and are induced by a wide array of tumor- and stroma-derived factors, including TGF-β, IL-6, IL-17, CXCL2, prostaglandin E2 (PGE2), granulocyte colony-stimulating factor (G-CSF), GM-CSF, and hyaluronic acid (HA) fragments." (PMID 40805288, 2025). "SE modulated IL-2, IL-4, IL-6, IL-17, IFN-γ, and TNF-α in tumor environment." (PMID 40807278, 2025). "In cell cultures and animal models, NF-κB is activated and upregulated during inflammation, thus boosting the expression of several pro-inflammatory cytokines such as IL-1β, IL-6, COX-2, and TNF-α and altering tumor inflammatory microenvironment to promote tumor cell survival." (PMID 39834867, 2025). "The subsequently pro-inflammatory state is a crucial link between adipose tissue and cancer cells, offering novel insights into potential therapeutic strategies, such as targeting IL-6, IL-8, and MCP-1 to disrupt the interaction between adipose tissue and tumour cells." (PMID 40414892, 2025). "Compounding this, platinum treatment may activate the STAT3 pathway by increasing IL-6, IL-10, and PGE2 production, leading to M2 polarization and tumor progression." (PMID 41280929, 2025). "Moreover, iCAFs showed interaction with surrounding T cells by secreting IL-6 and CXCL12, leading to establishment of a tumour-favourable microenvironment in gastric cancer." (PMID 39780187, 2025). "Doenjang significantly reduced tumor formation and attenuated CAC progression by modulating inflammatory and apoptotic pathways and suppressed the expression of pro-inflammatory cytokines (TNF-α, IL-1β, and IL-6) by inhibiting the NF-κB pathway." (PMID 41154100, 2025). "The limited efficacy of global IL‐6 blockade in alleviating cancer cachexia symptoms without halting tumor progression is further supported by observations from the LLC cachexia model." (PMID 39764565, 2025). "Recently, PRMT6 has been found to promote breast cancer metastasis through asymmetrical di-methylation of the signal transducer and activator of transcription 3 (STAT3), which activates downstream signaling in the IL-6/STAT3 pathway, contributing to tumor metastasis and invasion." (PMID 39908270, 2025). "Noteworthy, TNF-α and IL-6 seem to stimulate MAO-B expression in normal human prostate stromal fibroblasts, pointing to a possible mechanistic link between MAO isoforms in the initial communication between tumor cells and normal stroma." (PMID 39714760, 2025).
tumor (continued). "Due to their major role in the tumor cell progression, the levels of the pro-inflammatory cytokines TNF-α and IL-6 were evaluated in dynamics during Nivolumab treatment in three selected serum samples (T1–T3, timepoints of Nivolumab treatment) from each patient at 3-month intervals." (PMID 40564098, 2025). "When comparing the low IL-6 group with the high IL-6 group, the low IL-6 group had better PS and included cases with good liver reserve, but no significant items were found regarding tumor factors." (PMID 39652104, 2025). "Furthermore, spatial transcriptomics on human PDAC tissue revealed that iCAFs using gene markers IL6 and CXCL12 and myCAFs using gene markers ACTA2 and MMP11 were spatially distributed and correlate with tumor and immune cell localizations." (PMID 41376815, 2025). "For instance, IL-6 stimulates VEGF secretion to foster angiogenesis and activates CAFs to produce matrix metalloproteinases (MMPs) and collagenases, which degrade the basement membrane and facilitate tumor cell migration." (PMID 41394847, 2025). "As a key pro-inflammatory cytokine in the tumor microenvironment, IL-6 plays a dual role in promoting CAF activation and creating a favorable environment for tumor cell proliferation and metastasis.The activation of CAF is a critical step in the process of tumourigenesis and progression." (PMID 40364836, 2025). "Furthermore, B7-H3 upregulation increased the production of Th1/Th2 cytokines (including TNF-α, IL-2, IL-4, IFN-γ, IL-6, and IL-10) in the TME and triggered TNF-α secretion in CRC cells, contributing to tumor growth." (PMID 40214484, 2025). "As MSN contains a FERM domain identically found in JAK2 and IL-6 stimulates hyperactivation of JAK signaling, we next examined whether IL-6 acts on tumor cells to activate MSN." (PMID 40696387, 2025). "During the initiation phase, OGP significantly attenuated adenomagenesis in both the small and large intestine, decreased IL-6 and IL-4 levels, increased splenic anti-tumor CD8+ T cells, and diminished populations of tumor-promoting myeloid-derived suppressor cells." (PMID 40307509, 2025). "IHC staining disclosed a significantly suppressed expression of senescence marker P21 and SASP cytokines like IL6 and IL1β in tumor samples, regardless of GDC-0879 mono- or combined therapy with anti-PD1." (PMID 40781221, 2025). "Pro-inflammatory cytokines such as interleukin-1 beta (IL-1β), interleukin-6 (IL-6), and tumor necrosis factor-alpha (TNF-α)—primarily secreted by macrophages and other immune cells in the TME—are instrumental in both tumor progression, systemic immune modulation, and renal function." (PMID 41301732, 2025). "Moreover, in the tumor microenvironment, activation of the JAK/STAT3 pathway by IL-6 occurs in both cancer cells and infiltrating immune cells, which can contribute to tumor progression." (PMID 40643463, 2025). "Moreover, key cytokines and chemokines, including IL-6, IL-10, IL-8, TNF-α, TGF-β, and CCL2/5, demonstrate subtype-specific and context-dependent effects, acting as both tumor-promoting and tumor-suppressing agents through complex signaling networks." (PMID 40909271, 2025). "Specifically, TAS-115 alone and in combination with DOXO significantly reduced the levels of key pro-inflammatory cytokines, including TNF-α, IL-1α, and IL-6, which are often elevated in the TME and contribute to tumor progression, therapy resistance, and immunosuppression." (PMID 41289612, 2025).